IFI27 (interferon alpha inducible protein 27)
Diseases named in the same sentence as IFI27 in open-access papers (continued):
Sharing a sentence is not in itself a finding about the gene and the disease.
infection (continued). "The increased expression of IFI27 in the replication–transcription complex-specific T cells of seronegative healthcare workers indicates the early characteristics of SARS-CoV-2 and contributes to the clearance of the virus during infection." (PMID 35928229, 2022). "Infection with either HO or KY alone had similar inhibitory effects on most ISGs (ISG15, GBP4, HERC5, RSAD2, DDX58, and IFIT3), although a slightly greater inhibitory effect of HO was observed on IFI27 and MX1." (PMID 33898551, 2021). "Also, it was important to discuss thatthough our study identified a total of 9 genes that were common among three stages, but only 6 of them (OASL, IFI27, IFIT1, IFIT3, RSAD2and IFI44L) made into the PPI network whose expression level increases with the increase in the level of infection." (PMID 40255307, 2025). "Expression levels of RSAD2, ISG15, IFI44L, and IFI27 were strongly correlated to serum sCD163 levels early after infection, but not to T-cell activation, suggesting that ISG expression may be linked to monocyte activation." (PMID 39104769, 2024). "Other ISGs regulated by rDEN2Δ30 infection such as ISG15 and IFI27 have not been well-documented in natural infection though may play a role in controlling viral replication among other functions." (PMID 34031380, 2021). "Therefore, upon infection with viruses not encoding PKR antagonists, such as viruses lacking these proteins, IFI27 may lead to a stronger modulation of PKR activation." (PMID 40522981, 2025). "A hard-thresholded, mostly relaxed, LASSO-constrained logistic regression model was used to select a parsimonious gene set (ITGB4, ITGA7, IFI27, FAM20A) highly capable of discriminating any bacterial from nonbacterial infection (cross validated AUC = 0.90)." (PMID 40060038, 2025). "In addition, we show that IFI27 overexpression at high levels, promotes PKR phosphorylation even in the absence of infection, and in the absence of infection in conditions of PKR overexpression; and that the knock-out of IFI27 can decrease PKR phosphorylation." (PMID 40522981, 2025). "UV inactivation of HBV abolishes the block in innate immune activation, as evident by the increased levels of IFI27 and IFITM3 mRNA in the absence of HBV replication 10 days postinfection, supporting that direct immune evasion of HBV occurs early during infection." (PMID 29445209, 2018). "However, the majority of antiviral ISGs, including OAS1, MX2, IFI6, IFITM1, IFI27, and IFTM2, were downregulated in cells transduced with MyD88 (in the presence or absence of infection) and were also downregulated in cells infected with UL88-deficient HCMV vs wild-type HCMV." (PMID 40638072, 2025).
tumor (72 papers, 2009 to 2026). "Our analysis suggests that when considering both TGFB2 and IFI27 gene methylation as prognostic markers, the mRNA correlation with gene methylation yielded potential diagnostic markers markedly upregulated in tumor tissues." (PMID 40565031, 2025). "SpaCET-based malignant subtyping identified IFI27 as a hallmark of high-grade malignancy subcluster B (tumor purity > 80%, p < 1 × 10−5)." (PMID 41008826, 2025). "In contrast, IFI27, a gene associated with the interferon pathway, was closely linked with tumor development and the regulation of T lymphocytes in the immune microenvironment." (PMID 39668835, 2024). "Taken together, these data suggest that PABPC1-induced tumor progression is associated with IFI27 expression." (PMID 35346324, 2022). "PPIB, UGT2B15 and IFI27, which were found in tumour cluster A, were mainly associated with cell survival and apoptosis." (PMID 35109839, 2022). "We conducted a comprehensive analysis of data from TCGA, GEO and GTEx, and we found that a significantly increased expression of IFI27 in tumor tissues was associated with worse overall survival in patients with PAAD." (PMID 34592906, 2021). "IFI27 is highly expressed in cell-rich regions, and carcinoma-associated fibroblasts (CAFs) isolated from these cell-infiltrated subregions display enhanced motility and greater tumor-proliferative capacity." (PMID 41008826, 2025). "Notably, high STING scores are associated with enhanced tumor-promoting pathways, active immune interactions, and enrichment in fibroblasts and IFI27+ inflammatory macrophages." (PMID 40308576, 2025). "These genes were highly enriched for immune response and adhesion by GO terms, including genes such as IFI27 (encoding Interferon alpha inducible protein 27, which can act also as a tumor suppressor) and SIGLEC10 (encoding sialic acid-binding Ig-like lectin 10)." (PMID 37024521, 2023). "IFI27 is known to be one of the most widely upregulated genes in cancer and plays a role in apoptosis, metabolism, the cell cycle, and tumor growth and suppression." (PMID 40224214, 2025). "At the same time, the expression of MHC class I-related molecules (H2-D1, H2-K1, H2-T23) and the immune response-related genes Irf7, Ifi27 was increased in Il1r2−/− mouse tumor cells." (PMID 40767963, 2025). "The most significantly downregulated gene of posttreatment tumor cells and macrophages in patients with recurrence was IFI27, which plays diverse roles in antitumor immunity." (PMID 40900789, 2025). "Two representative overlapping genes, IFI27 and NBEAL1, were significantly associated with poor patient prognosis (IFI27, p = 0.0116; NBEAL1, p = 0.0196), suggesting their potential roles in tumor progression." (PMID 41465457, 2025). "While PCR validation on matched tumor/normal tissues confirmed significant differential expression of IFI27, KIF20A, KLK10, and TOP2A." (PMID 41008826, 2025). "Tumor cell characterization revealed that Ep3 cells exhibit high expression of interferon‐related genes (IFI27, IFI6) and are involved in antiviral immune responses, cellular stress, immune regulation, and cholesterol homeostasis." (PMID 40552583, 2025). "The STING-related pathway exhibited distinct expression levels across 15 cell populations, with high-score cells showing enhanced tumor-promoting pathways, active immune interactions, and enrichment in fibroblasts and IFI27+ inflammatory macrophages." (PMID 40308576, 2025). "To assess the potential role of IFI27 in BCa lymph node metastasis in vivo, we inoculated tumor cells into the footpad of nude mice, establishing a footpad-popliteal lymph node model." (PMID 39668835, 2024). "Representative bioluminescence images taken two to three weeks after injection showed that IFI27 overexpression inhibited tumor growth compared to the control group." (PMID 39668835, 2024).
tumor (continued). "Since IFI27 contributes to the anti-tumor immune response, this study focuses on how IFI27 modulates the immune microenvironment and the development of malignancy in BCa." (PMID 39668835, 2024). "In summary, we demonstrated that overexpression of IFI27 inhibits BCa growth by reducing the infiltration of Treg cells in the tumor parenchyma through the suppression of FOXP3 expression in Treg cells." (PMID 39668835, 2024). "Statistical analysis of tumor weight and volume revealed that IFI27 overexpression suppressed xenograft tumor growth, resulting in reduced tumor weight and volume compared to controls." (PMID 39668835, 2024). "The results showed that IFI27 was significantly correlated with tumor clinical stage, tumor infiltration, lymph node metastasis, and distant metastasis." (PMID 39668835, 2024). "Volume and weight measurements of these lymph nodes indicated that IFI27 overexpression attenuated tumor lymphatic metastasis." (PMID 39668835, 2024). "IFI27 displayed the highest-fold change in all the genes examined relative to normal tissue and one of the most abundant genes in tumor tissue." (PMID 39457004, 2024). "Given its crucial role in modulating the immune response and influencing the effectiveness of tumor immunotherapy 34, 36, we further investigated the correlation between IFI27 and clinical features of BCa." (PMID 39668835, 2024). "To further validate the involvement of Treg cells in the IFI27-mediated promotion of anti-tumor immunity, we collected mouse spleens, tumor tissues, and peripheral blood." (PMID 39668835, 2024). "All in all, the correlation between IFI27 expression and FOXP3 was supported by clinical samples and TCGA BCa patient data, suggesting that the IFI27/PD-1/FOXP3 axis was involved in the modulation of anti-tumor immune processes in BCa." (PMID 39668835, 2024). "Previous studies have confirmed IFI27 as a critical immune regulatory gene, promoting cancer immunity by increasing the sensitivity of tumor cells to the cytotoxic effects of human immune cells, thus exerting an inhibitory effect on cancer development." (PMID 39668835, 2024). "Over the past decade, IFI27 has been reported to promote tumor cell growth and migration in several cancers." (PMID 38300891, 2024). "Two weeks after tumor cell injection, bioluminescence imaging showed a lower footpad signal in the IFI27 overexpression group compared to the control group, although signals in the popliteal lymph nodes were barely detected." (PMID 39668835, 2024). "Statistical analysis of bioluminescence intensity revealed significant inhibition of tumor proliferation in immunocompetent mice with IFI27 overexpression." (PMID 39668835, 2024). "IFI27 expression was significantly higher in ESCC tissues compared to paired non-tumor tissues in the GSE20347 (n = 34) and GSE23400 cohorts (n = 106), as well as in our ESCC cohort detected by western blotting (n = 24) and immunohistochemistry (n = 190)." (PMID 35346324, 2022). "Overexpression of IFI27 promotes cancer cell proliferation and tumor growth, while its knockdown exhibits the opposite effect." (PMID 35267998, 2022). "The IFIT1, ISG15, IFITM1 and IFI27 genes are related to activation of the interferon gamma (IFNγ) response, suggesting possible inflammatory responses in NR tumour samples." (PMID 35053540, 2022). "To further evaluate the effects of PABPC1 and IFI27 on tumor growth, we established xenograft mouse models of ESCC (6 mice per group)." (PMID 35346324, 2022). "According to TCGA-BRCA data, the expression of the positive genes of risk score (HJURP, IFI27, RAD51AP1, EZH2, DNMT3B, SLC7A5, DBF4 and USP18) in tumors was higher than that in normal and tumor-adjacent tissues." (PMID 36341435, 2022). "It has been reported that IFI27 protein plays diverse roles in anti-tumor immunity, including suppressing the transcription of PD-L1 and promoting epithelial–mesenchymal transition." (PMID 35820705, 2022).
tumor (continued). "Of the six genes identified, IFI27, IFI6, IFITM1, ISG15, and BST2 have been reported to be associated with cancer cell proliferation and tumor growth." (PMID 35267998, 2022). "In situ hybridization to some of the IFI27-overexpressing tumors showed that IFI27 mRNA is localized in cancer cells and sometimes also in fibroblast cells of the tumor stroma." (PMID 34592906, 2021). "M2 macrophages have been reported to promote tumor progression, and we found that M2 macrophage infiltration is increased in patients with high IFI27 expression." (PMID 34592906, 2021). "Verification with a mouse orthotopic model verification showed that IFI27, glycolysis and M2 macrophages were significantly up-regulated in tumor tissues." (PMID 34592906, 2021). "The figure showed that compared with normal pancreatic tissues, IFI27 displayed up-regulation in tumor tissues." (PMID 34592906, 2021). "Then, the role of endogenous IFI27 in tumor invasion, migration, and growth was investigated in vitro." (PMID 33824473, 2021). "IFI27 (interferon alpha‐inducible protein 27) is involved in tumor apoptosis signaling pathways, including type‐I interferon‐induced apoptosis and TNFSF10‐induced apoptosis, and regulates the innate immune response." (PMID 33955587, 2021). "It was reported that in a variety of cancers, the downregulation of IFI27 affects tumor development." (PMID 29580248, 2018). "Among the tumor related factors seen in tumor free tissue, the gene ontology terms cellular response to type I interferon and type I interferon – mediated signaling pathway including IFI27 are seen." (PMID 28038473, 2017). "The top gene based on FC when comparing tumor free tissue and control was interferon alpha-inducible protein 27 (IFI27) which is involved in the type I interferon signaling pathway." (PMID 28038473, 2017). "Interestingly, using IFI27 knocked-down, knocked-out and overexpressing tumour-derived, established cells, we show that these interactions trigger a potentiation of the activity of PKR and, therefore, a decrease in protein translation." (PMID 40522981, 2025). "Furthermore, C20orf204 and IFI27 were expressed in both the tumor and stromal regions, highlighting their broad relevance across these areas." (PMID 39135097, 2024). "Many downregulated genes in tumour‐infiltrating peripheral CD8+ T cells are associated with classical IFN responses (IFI6, IFI27, MX1, STAT1, EPSTI1 PARP9, ISG15), cell proliferation (STMN1, CENPF, HELLS, NUSAP1, and DNPH1), and T cell costimulation (CD28, TMIGD2, TNFRSF4, CD27, and TNFRSF18)." (PMID 39350478, 2024). "Additionally, IFI27 contributes to anti-tumor immune responses by reducing the infiltration of regulatory T cells (Treg) into the tumor stroma." (PMID 39668835, 2024). "Moreover, IFI27 overexpression enhances the inhibitory effect of PD-1 antibody immunotherapy, with a more pronounced suppression of tumor growth." (PMID 39668835, 2024). "Additionally, among the upregulated genes, we identified genes that have increased expression in metastatic cancer cells, such as the BST2 gene, or promote cancer cell migration, tumor growth, and angiogenesis like IFI27." (PMID 39405604, 2024). "In fact, IFI27 is a potential prognostic marker and therapeutic target for cancer and tumor growth." (PMID 35267998, 2022). "IFI27 is involved in signaling pathways of apoptosis and type-I interferon, while the downregulation of IFI27 may enhance the ability of tumor cells to survive." (PMID 36474268, 2022). "The development of tumours can be affected by IFI27 downregulation in many cancers." (PMID 35109839, 2022). "In addition, the ‘CIBERSORT’ algorithm and single-gene function enrichment analysis also showed that IFI27 is related to immune cell infiltration and glycolysis in the tumor microenvironment." (PMID 34592906, 2021).
tumor (continued). "The GSEA enrichment analysis of IFI27 also shows that IFI27 is mainly involved in cellular immune responses and cell metabolism, which suggest that it may promote tumor progression." (PMID 34592906, 2021). "IFI27 has been also shown to play a tumor promoting function in multiple cancers and the knockdown of IFI27 was reported to inhibit the proliferation and invasion of TSCC cells, but the underlying molecular mechanism by which IFI27 regulates tumor cell growth and migration is still not clear." (PMID 33539340, 2021). "Low expression of IFI27 in tumor free tongue tissue thus indicates better survival." (PMID 28038473, 2017). "Furthermore, increased expression of a subset of ISGs, including IFITM1, EIF2AK2, STAT1, and IFI27, has been reported in several types of cancers, and these ISGs have been shown to promote tumor growth and resistance to chemotherapy and radiotherapy." (PMID 26897526, 2016). "We speculate that EBV-infected cells require the IFI27-mediated growth resilience to overcome stresses such as anti-viral responses upon primary infection, and hypoxic and hypovascular circumstances in the tumor." (PMID 38300891, 2024). "Therefore, tomatidine and TRTLE may contribute to the inhibition of cancer cell growth and tumor formation through the downregulation of expression of ISGs, such as IFI27." (PMID 35267998, 2022). "In addition, we found that IFI27, as a new biomarker, may affect the tumor microenvironment, especially by promoting the decrease of CD8 + T cells and the increase of M2 macrophages." (PMID 34592906, 2021). "IFI6, IFI27, OAS1, and OAS3 are part of the interferon-alpha response (IFN-α) pathway, known for its anti-tumor and anti-viral immune responses." (PMID 39809731, 2025). "Such ubiquitous expression was shown by IFN-α–inducible protein 27 (IFI27), despite its emergence among the top-ranked CUGs in PDAC and as tumor-specific in other comparisons." (PMID 39774001, 2025). "IFI27, KIF20A, KLK10, and TOP2A were highly expressed in tumor cells, supporting their potential as prognostic biomarkers in PAAD." (PMID 41008826, 2025). "Single-cell and spatial analyses revealed cellular specificity (e.g., IFI27/KLK10 in ductal cells/fibroblasts) and tumor-region-specific expression patterns." (PMID 41008826, 2025). "The highest levels of expression in tumor tissue were observed for CD74 (Mean ± SEM = 10.94 ± 0.08), IFI27 (Mean ± SEM = 9.63 ± 0.12), and HLA-DRA (9.3 ± 0.1)." (PMID 39457004, 2024). "IFI27 is one of the most significantly upregulated genes in the PDAC TME (66.3-fold increase), with high levels of expression in tumor tissue (Mean ± SEM = 9.63 ± 0.12 log2 TPM), suggesting its potential to serve as a prognostic biomarker in these patients." (PMID 39457004, 2024). "In vivo results show that IFI27 inhibits the Treg cell-specific marker FOXP3, thereby hindering Treg cell recruitment to the tumor and immune organs." (PMID 39668835, 2024). "IFI27, LCN2, GAST, and SERPINA1 were downregulated after NACT in tumor cells, while OLFM4, MRPS35, MMP1 and MED21 were upregulated in tumor cells." (PMID 36474268, 2022). "In sporadic PMF patients, IFI27 was overexpressed, reflecting the facilitation of PMF activity and enhancement of the tumor burden." (PMID 35798703, 2022). "Specifically, in the tumour region, we observed enrichment of PPIB and UGT2B15 and IFI27, NDRG1, BHLHE40 and VEGFA." (PMID 35109839, 2022). "While IFN-α itself was not differentially expressed in the PD laryngeal SCC, IFI6 and IFI27, two type I IFN-α stimulating genes, showed significantly higher expression in this new tumor." (PMID 36210388, 2022). "IFI27 was found to be closely related to the clinical progression of PAAD, as well as tumor glycolysis and infiltration of M2 macrophages." (PMID 34592906, 2021). "The results demonstrate that ATF3 plays a tumor suppressing function in TSCCs through the negative regulation of its novel targets IFI6 and IFI27." (PMID 33539340, 2021).